MTOR (mechanistic target of rapamycin kinase)
Diseases named in the same sentence as MTOR in open-access papers (continued):
Sharing a sentence is not in itself a finding about the gene and the disease.
lysosomal storage disorders (11 papers, 2013 to 2025). "First, this clinical research illustrated the significant association between ERS and mTOR pathway mediated autophagic-lysosomal disorder, but the detailed mechanisms are still unclear and need further study." (PMID 40933998, 2025). "mTOR pathway mediated autophagic-lysosomal disorder showed significant association with CTLA-4 expression." (PMID 39104530, 2024). "SPNS1 encodes a lysosomal efflux transporter that regulates mTOR signaling and whose loss‐of‐function is associated with lysosome storage disorders." (PMID 36124427, 2022). "ERT treatment improves HSPG2 levels, recently associated with lysosomal storage disorders and involved in the regulation of autophagy mediated by mTOR signaling." (PMID 33799647, 2021). "ERS was strongly associated with mTOR pathway mediated autophagic-lysosomal disorder." (PMID 40933998, 2025). "As LC3II was also found to be significantly different, which was a biomarker of mTOR pathway mediated autophagic–lysosomal disorders, we hypothesized that this disorder might be associated with differing expression levels of CTLA-4 on CD4+ lymphocytes." (PMID 39104530, 2024). "In the future, larger patient sample, clinical intervention research and animal experiment could test the association between CTLA-4 and mTOR pathway mediated autophagic-lysosomal disorder." (PMID 39104530, 2024). "The discovery of a link between the lysosome and mTOR activation/inactivation opens a new frontier for investigation into the role of this kinase in the pathogenic cascades in lysosomal storage diseases (LSDs)." (PMID 28130275, 2017). "Thereafter, we hypothesized that mTOR pathway mediated autophagic-lysosomal disorder might be significantly associated with differing expression levels of CHOP on CD4+ lymphocytes, and the overexpression of CHOP might be statistically correlated with CD4+ T lymphocyte reduction." (PMID 40933998, 2025). "The recent finding that the decision regarding its activation/inactivation takes place at the lysosome undeniably brings mTOR into the field of lysosomal storage diseases." (PMID 28130275, 2017). "The relevance of mTOR signaling to the pathogenesis of this lysosomal storage disorder is further emphasized by recent well‐documented data showing a link between mTOR activity and lysosomal function." (PMID 28130275, 2017). "Our study confirmed that CTLA-4 expression on CD4+ cells might also be modulated by mTOR pathway mediated autophagic lysosomal disorder." (PMID 39104530, 2024). "This study was designed to illustrate the association between CTLA-4 expression on CD4+ lymphocytes and the occurrence of SAI and prognosis of patients with SAI, and furthermore to clarify the relationship between mTOR pathway mediated autophagic–lysosomal disorder and CTLA-4 expression." (PMID 39104530, 2024). "Reinstatement of mTOR activity by arginine may prove an effective strategy for Pompe disease as well as for a large group of neuromuscular and lysosomal disorders." (PMID 28130275, 2017). "In fact, a recent study has reported that there is a relationship between the up-regulation of Akt/mTOR and ERK signaling pathways and the increased ROS activity in other lysosomal storage disorders." (PMID 24340026, 2013).
neurofibroma (11 papers, 2012 to 2023). An intraneural or extraneural neoplasm arising from nerve tissues and neural sheaths. "Clinical trials on other MEK1-2 inhibitors alone or in combination with mTOR inhibitors are under investigation in plexiform neurofibromas and MPNST, respectively." (PMID 37046591, 2023). "Both the RAS-ERK and PI3K-Akt-mTOR signaling pathways thus appear to play key roles in the malignant transformation of neurofibroma into MPNST." (PMID 35625983, 2022). "Preclinical studies have been conducted in models of neurofibromas and MPNSTs using mTOR inhibitors that suggest varied efficacy at different stages of disease." (PMID 24681606, 2014). "While loss of NF1 is clearly functioning to drive benign neurofibromas, it appears that further activation of Ras/PI3K/AKT/mTOR signaling is required for malignant transformation." (PMID 24681606, 2014). "Based on these studies, phase II clinical trials are currently in progress using the mTOR inhibitor rapamycin in the treatment of plexiform neurofibromas." (PMID 24681606, 2014). "Elevated mTOR activity has been observed previously in MPNSTs and neurofibromas and is currently the subject of multiple clinical trials (NCT00634270, NCT01661283, NCT00652990)." (PMID 24040940, 2013). "It has been shown that activation of mTOR pathway in nerve sheath tumor cell lines is essential for neurofibroma formation." (PMID 23145129, 2012). "The aim of this study was to evaluate Pten alterations in human MPNST and neurofibroma and possible consequences for treatment with mTOR inhibitors." (PMID 23139750, 2012). "Analysis of human Schwann cell tumors and mouse models of neurofibromas and MPNSTs have demonstrated the functional importance of both PI3K/AKT/mTOR and MAPK pathway activation." (PMID 24681606, 2014). "Future work will also need to be done to study the effect of co-targeting mTOR and MEK in other less severe models of neurofibromas or MPNST development, including other GEMMs as well as xenograft models." (PMID 24681606, 2014). "Here we examined the role of Pten, a key regulator of the Pi3k/Akt/mTOR pathway, in human MPNST and benign neurofibromas." (PMID 23139750, 2012). "Although topical and systemic sirolimus is very efficacious for another mTOR-activating inherited genetic disorder, tuberous sclerosis, sirolimus failed to reduce the neurofibroma volume in progressing and non-progressing neurofibromas." (PMID 34011935, 2021). "Although these pathways are believed to induce the proliferation of neurofibroma cells and COL1A1 production, leading to neurofibroma formation, the therapeutic outcomes of the specific mTOR inhibitor sirolimus and the anti-collagenogenic pirfenidone in clinical trials have not been satisfactory." (PMID 34011935, 2021). "The RAF/MAPK and PI3K/AKT pathways both activate mTOR signalling, a process found to be highly regulated in neurofibromas whereby mTOR pathway activation occurs in the absence of growth factors, in both NF1 tumours and neurofibromin-deficient cultured cells." (PMID 28637487, 2017). "BRAF inhibitors, such as sorafenib exhibited significant toxicity in NF1 patients in clinical trials, whereas mTOR inhibitor sirolimus did not affect tumor burden, although it prolonged time to disease progression by four months in plexiform neurofibroma patients." (PMID 27494873, 2016).
neutropenia (11 papers, 2010 to 2025). A decrease in the number of neutrophils found in the blood. "The use of mTOR inhibitors has been associated with haematological adverse events such as thrombocytopenia and leucopenia/neutropenia and, hence, their use requires routine complete blood counts." (PMID 37513916, 2023). "In the endocrine treatment and mTOR inhibitor (ET + mTORI) group, neutropenia was much less common (11.1%; n = 3) and was grade 1 in only two patients and grade 2 in one." (PMID 41156245, 2025). "However, due to grade 3 neutropenia, the chemotherapy was discontinued and temsirolimus (25 mg once weekly), which binds to the cytoplasmic protein, FKBP-12, and inhibits mTOR, was administered." (PMID 24959297, 2014).
pheochromocytoma (11 papers, 2015 to 2026). "TMEM127 is a tumour suppressor gene (four exons, chromosome 2q11) linked with mTOR (mammalian target of rapamycin) kinase pathway which has recently been associated with the development of phaeochromocytoma." (PMID 29166454, 2017). "Everolimus, an mTOR inhibitor, has shown some efficacy in reducing lesion size in a subset of pheochromocytomas such as NF1 patients." (PMID 40649858, 2025). "For example, microRNA-210 overexpression is seen in pseudohypoxia-related pheochromocytoma, whereas microRNA-21-3p levels correlate with mTOR activation, potentially predicting response to mTOR inhibitors." (PMID 40649858, 2025). "Pharmacological activation of AKT or mTOR partly prevented GO-mediated LC3-I/LC3-II conversion in pheochromocytoma cells, confirming the role of AKT/mTORC1 signaling axis in GO-induced autophagy." (PMID 34439299, 2021). "As further evidence of this link, it has been shown that the mTOR pathway is commonly activated in both paraganglioma and pheochromocytoma tumors." (PMID 29671738, 2018). "A study of its normal and mutant forms in pheochromocytomas showed this protein to function as a negative regulator of mTOR." (PMID 28187001, 2017). "mTOR is a crucial downstream signal of both RAS and RET pathways, and is aberrantly activated in NF1-deficient malignant peripheral nerve sheath tumours, phaeochromocytomas and paragangliomas." (PMID 29166454, 2017). "Despite the apparent importance of PI3K/Akt/mTOR signaling in phaeochromocytoma, there has been limited experience and success in targeting this pathway clinically." (PMID 26793165, 2015). "Loss-of-function mutations in TMEM127 lead to abnormal mTOR signaling activities and tumor development, frequently linked to adrenal-based pheochromocytomas in patients, often without a family history." (PMID 40649858, 2025). "The inhibition of pheochromocytoma cell proliferation and tumor growth by the suppression of PI3K/Akt/mTOR has also been demonstrated in a number of in vitro studies, indicating its functional role in tumorigenesis." (PMID 39684472, 2024). "Autophagy activation in lung carcinoma cells exposed to amino-functionalized GQD coincided with the inhibition of AKT, while the treatment of pheochromocytoma and glioma cells with GO suppressed both AKT and mTOR." (PMID 34439299, 2021). "In particular, as the mTOR protein represents an important target of the RAS pathway; therefore its unregulated activation is typical of NF1-mutant paragangliomas/pheochromocytomas." (PMID 28187001, 2017). "Further evidence of altered PI3K/Akt/mTOR signaling is suggested by increased expression of S6K1 and reduced expression of p27KIP1 in human pheochromocytoma compared with normal tissue and elevated pS6 in metastatic tumors." (PMID 26793165, 2015). "Previous studies have indicated that MPH may also affect adjacent signaling pathways related to Wnt, such as Akt/mTOR pathway components (e.g., S6K and 4E-BP1) in rat pheochromocytoma cells." (PMID 40719827, 2026). "mTOR inhibitor AZD8055 significantly reduced the tumor and metastatic burden in athymic nude mice injected with cells of the metastatic mouse pheochromocytoma-derived cell line, MTT, and decreased survival of primary human pheochromocytoma cells in culture." (PMID 26793165, 2015). "The role and functions of mTOR and its signaling pathway in the normal and tumoral adrenal gland have not been completely clarified but a dysregulation of AKT, leading to growth-simulating effects, has been described in adrenocortical carcinomas and pheochromocytomas." (PMID 39199391, 2024). "Additional support for the relationship between TMEM127 and mTOR may be surmised from the elevated phosphorylation of mTOR targets both in cell lines lacking TMEM127 and in human pheochromocytomas with mutations in this gene." (PMID 28187001, 2017).
premature ovarian failure (11 papers, 2016 to 2026). "First, it is known that proper mTOR activity is essential for follicle reserve, and excessive mTOR activity could cause premature ovarian failure and follicle atresia." (PMID 31389140, 2019). "CDK12 has been also shown to play a role in the PI3K/AKT/mTOR pathway, which is a critical signaling cascade involved in primary ovarian insufficiency (POF)." (PMID 40148269, 2025). "It was also confirmed that mTOR inhibitors can promote follicular quiescence and prevent premature ovarian failure when used in cyclophosphamide-induced and cisplatin-induced ovarian dysfunctional animal models." (PMID 31649622, 2019). "Additionally, ADSCs transplantation inhibits the PI3K/Akt/mTOR signaling pathway, leading to reduced apoptosis and senescence of granulosa cells, increased follicle counts, and enhanced hormone secretion, effectively alleviating chemotherapy-induced premature ovarian failure (POF)." (PMID 40402971, 2025).
RASopathies (11 papers, 2017 to 2025). "Research on disease models has shown that signaling inhibitors of the MEK/ERK and AKT/mTOR pathways are therapeutic drug candidates for RASopathies." (PMID 39352760, 2024). "Three classes of rare genetic disorders, TSC, RASopathies, and cilyopathies, are described in detail, and the dysregulated pathways are described, namely the mTOR, the RAS/MAPK, and the Wnt patwhays, respectively." (PMID 36982349, 2023). "RASopathy patients exhibit alterations in the expression and activation of proteins in several signaling pathways, including RAS/MAPK, PI3K/AKT/mTOR, Rho/ROCK/LIMK2/cofilin, cAMP/PKA, JAK/STAT, Hippo, Wnt/β-catenin, and TGF-β." (PMID 39201250, 2024). "mRNAs, non-coding RNAs, protein expression patterns, and post-translational modifications characteristic of RASopathy patients within pivotal signaling pathways such as the RAS/MAPK, PI3K/AKT/mTOR, and Rho/ROCK/LIMK2/cofilin pathways are summarized." (PMID 39201250, 2024). "Due to the crosstalk between the PI3K/AKT/mTOR and RAS/MAPK pathways, phosphorylation levels of AKT, S6RP, and mTOR have been previously used as biomarkers in research on RASopathies." (PMID 39201250, 2024). "RASopathies are a group of rare genetic conditions defined by germline alterations in the RAS-MAPK pathway that often result in constitutive activation of the phosphoinositide 3-kinase (PI3K), RAF and mammalian target of rapamycin (mTOR) pathways located downstream of RAS." (PMID 39016685, 2024).
Seizure (11 papers, 2013 to 2025). A seizure is an intermittent abnormality of nervous system physiology characterized by a transient occurrence of signs and/or symptoms due to abnormal excessive or synchronous neuronal activity in the brain. "Seizures themselves may directly cause acute activation of the mTOR pathway." (PMID 23437388, 2013). "Epileptic seizures are a progressively worsening and dynamic process in which several cellular, molecular and pathophysiological mechanisms may be involved, including mammalian target of rapamycin (mTOR) dysregulation and synaptic abnormalities." (PMID 38419709, 2024). "A selective 5-HT6R antagonist was able to attenuate spontaneous recurrent seizures in the post-SE pilocarpine rat model, and diminished hippocampal mechanistic target of rapamycin (mTOR) activity, suggesting that 5-HT6Rs may mediate limbic seizures via mTOR signaling." (PMID 27891070, 2016).
acute lung injury (10 papers, 2018 to 2023). A condition of lung damage that is characterized by bilateral pulmonary infiltrates (pulmonary edema) rich in neutrophils, and in the absence of clinical heart failure. "The study focused on the protection of HRS on lipopolysaccharide (LPS)-induced acute lung injury (ALI) in rat models and the relationship with autophagic regulation and mTOR/TFEB signaling pathway." (PMID 32071922, 2020).
acute pancreatitis (10 papers, 2016 to 2026). An acute inflammatory process that leads to necrosis of the pancreatic parenchyma. "Spleen injury is caused by splenic ROS affecting PI3K/AKT/mTOR pathway-mediated autophagy in severe acute pancreatitis." (PMID 38582846, 2024). "miR-339-3p was reported to inactivate the Akt/mammalian target of rapamycin (mTOR) signaling pathway and to alleviate inflammation and edema caused by severe acute pancreatitis with acute lung injury in a mouse model by targeting annexin A3 (ANXA3)." (PMID 32264968, 2020). "Inhibiting CIP2A expression with TD52 and ethoxysanguinarine decreased the release of inflammatory cytokines, reduced macrophage apoptosis, promoted macrophage autophagy regulation, and inhibited the Akt-mTOR pathway in an in vitro model of acute pancreatitis." (PMID 41155727, 2025). "Inhibiting CIP2A expression with the CIP2A inhibitor TD52 reduced the release of inflammatory cytokines and apoptosis in macrophages and promoted macrophage autophagy regulation possibly via Akt/mTOR inhibition in an acute pancreatitis model." (PMID 41155727, 2025). "Researchers found that disruptions in lipid metabolism through pathways such as PI3K/AKT/mTOR/SREBP1 have been shown to aggravate metabolic inflammation, similar to what may occur in severe acute pancreatitis." (PMID 41425929, 2025). "It is noteworthy that in the mammalian target of rapamycin (mTOR) signaling pathway, the PI3K/AKT/mTOR axis plays a pivotal role, particularly mTOR complex 1 (mTORC1), which regulates the initiation of autophagy in acute pancreatitis (AP) through ULK1 phosphorylation." (PMID 40842993, 2025). "The enhancement of PNS on mTOR activation in severe acute pancreatitis rats may partly be explained by the fact that the extent of mTOR activation was significantly reduced, rather than increased, and PNS may have a restore effect on mTOR activation extent." (PMID 35003304, 2021).
autoimmune lymphoproliferative syndrome (10 papers, 2014 to 2025). Autoimmune lymphoproliferative syndrome (ALPS) is a rare, inherited disorder characterized by non-malignant lymphoproliferation, multilineage cytopenias, and a lifelong increased risk of Hodgkin's and non-Hodgkin's lymphoma. "Autoimmune lymphoproliferative syndrome with FAS mutations (ALPS-FAS) is also associated with hyperactivation of the mTOR pathway but hematologic symptoms are more severe than ALPS-CED." (PMID 41026346, 2025). "Caspase-8 enzyme deficiency (CED) is a rare autosomal recessive inborn error of immunity with autoimmune lymphoproliferative syndromes (ALPS), deficient extrinsic apoptosis and hyperactivation of the mammalian target of rapamycin (mTOR) pathway." (PMID 41026346, 2025). "Autoimmune lymphoproliferative syndrome (ALPS) is an mTOR‐driven lymphoproliferative disorder that uniformly responds to sirolimus, suggesting involvement of mTORC1 in pathogenesis." (PMID 35488725, 2022). "In autoimmune lymphoproliferative syndrome (ALPS) patients carrying mutations in FAS (ALPS‐FAS), we detected increased PI3K/AKT/mTOR activity in tissue‐resident B cells and an enhanced EF response, concomitant with strongly reduced GCs." (PMID 39917832, 2025). "Dysregulated mTOR signaling occurs in a variety of lymphoproliferative disorders, including autoimmune lymphoproliferative syndrome (ALPS), a disorder of lymphocyte survival due to defective apoptosis hallmarked biologically by double negative T-cells." (PMID 24904824, 2014). "We also found increased pNDRG1 expression in the germinal centers of iMCD-TAFRO compared to that in autoimmune lymphoproliferative syndrome (ALPS), an mTOR-driven sirolimus-responsive lymphoproliferative disease." (PMID 39451548, 2024). "Immunohistochemistry also revealed increased pNDRG1 expression in iMCD‐TAFRO germinal centres compared with autoimmune lymphoproliferative syndrome (ALPS), an mTOR‐driven, sirolimus‐responsive lymphoproliferative disorder, and comparable staining between iMCD‐NOS and ALPS." (PMID 35488725, 2022). "For example, in autoimmune lymphoproliferative syndrome type IA (ALPS-FAS), defective FAS signaling has been shown to impair mTOR activation and B cell differentiation without inducing apoptosis." (PMID 39843653, 2025).